IL17F (interleukin 17F)
Diseases named in the same sentence as IL17F in open-access papers (continued):
Sharing a sentence is not in itself a finding about the gene and the disease.
colon carcinoma (4 papers, 2012 to 2022). "To examine the roles of IL-17F in colon cancer, we have used IL-17F over-expressing colon cancer cell lines and IL-17F-deficient mice." (PMID 22509371, 2012). "IL-17F inhibited oral carcinoma cell proliferation, random cell migration and vasculogenic mimicry, controlled the cell cycle through p27 and p38, and diminished oxidative stress-causing G2/M phase arrest in colon carcinoma cells." (PMID 35012470, 2022). "Indeed, IL17F AG+GG mutated genotypes could protect against colon cancer unlike IL23R AC+AA mutated genotypes that could increase the susceptibility of colon cancer." (PMID 26083022, 2015). "In our search for the functional studies of IL-17F in cancer, we detected two interesting articles reporting opposite results about the role of IL-17F in colon cancer." (PMID 35012470, 2022). "To confirm that IL17F rs763780and IL23R rs10889677 polymorphisms were associated with the tumor location, we evaluate the relationship between colon cancer susceptibility and these two polymorphisms." (PMID 26083022, 2015). "Since IL-17F- and mock-transfected HCT116 cells exhibited similar in vitro proliferation kinetics, it is unlikely that IL-17F directly affects in vivo proliferation of the transplanted colonic tumors." (PMID 22509371, 2012). "Together, our findings demonstrate a protective role for IL-17F in colon cancer development, possibly via inhibiting tumor angiogenesis." (PMID 22509371, 2012). "In the current study, we found that IL-17F is expressed in normal human colonic epithelial cells, but this expression is greatly decreased in colon cancer tissues." (PMID 22509371, 2012). "In this study, by using both over-expression and deletion of IL-17F in colon cancer models, we suggest IL-17F has a protective role in colon tumorigenesis." (PMID 22509371, 2012). "Together, our findings suggest that IL-17F suppresses colon cancer development possibly via inhibiting tumor angiogenesis." (PMID 22509371, 2012). "To investigate the role of IL-17F in tumorigenesis, we stably transfected colon cancer cell line HCT116 cells with IL-17F cDNA and empty vector as control (mock transfectant)." (PMID 22509371, 2012). "We found that IL-17F is expressed in normal human colonic epithelial cells, which is down-regulated in colon cancer tissues." (PMID 22509371, 2012). "To further evaluate the role of IL-17F in tumorigenesis, we used AOM-DSS induced inflammation-associated colon cancer model in Il-17f−/−, Il-17a−/− and wild-type mice." (PMID 22509371, 2012). "Consistent with the mRNA data, we also found lower protein levels of IL-17F in colonic cancer tissues than corresponding normal tissues." (PMID 22509371, 2012). "In contrast, IL17F was down-regulated in human colonic cancer tissues." (PMID 26083022, 2015). "Association between IL17F/IL23R polymorphisms and colon cancer." (PMID 26083022, 2015). "To address the function of IL-17F in colon cancer, we evaluated IL-17F levels in the human colon cancer tissues and investigated the tumorigenesis by using IL-17F-transfected colon cancer cell lines in nude mice and a chemically-induced colon cancer model in Il-17f−/− mice." (PMID 22509371, 2012). "As a first step to determine the function of IL-17F in colon cancer, we analyzed colonic samples from colon cancer patients and found lower mRNA levels of IL-17F in cancer tissues when compared with corresponding normal tissues in the distal margin of the same surgical resection." (PMID 22509371, 2012). "Besides, over-expression of IL-17F inhibited the in vivo growth of HCT116 cells, an epithelial cell line derived from human colon carcinoma." (PMID 22509371, 2012). "On the other hand, IL-17a showed increased levels in IL-17F over-expression HCT116 cells and decreased levels in the colon tissues of AOM-DSS treated il-17f−/− mice, suggesting a compensatory regulation of IL-17F and IL-17A gene expressions in colon cancer." (PMID 22509371, 2012).
diabetes (4 papers, 2013 to 2025). "The potential explanation of this discrepancy is an additive effect of IL17F to diabetes pathogenesis, since the blocking antibodies were not specific to IL17A." (PMID 24013901, 2013).
juvenile idiopathic arthritis (4 papers, 2008 to 2024). Juvenile idiopathic arthritis (JIA) is the term used to describe a group of inflammatory articular disorders of unknown cause that begin before the age of 16 and last over 6 weeks. "Interleukin-17F (IL-17F), one of the cytokines, is crucial in the pathophysiology of juvenile idiopathic arthritis (JIA)." (PMID 36068342, 2023).
Sepsis (4 papers, 2012 to 2026). Sepsis is defined as life-threatening organ dysfunction caused by a dysregulated host response to infection. "The other “top genes” induced by sepsis in the spleen encode Semaphorin 3e (Sema3e), Interleukin-17F (Il17f), and Cytotoxic T lymphocyte antigen 4 (Ctla4)." (PMID 41229427, 2025). "In endothelial transcriptomic profiles of septic mice, we found a significant induction of Il17a and Il17f, identifying endothelial cells as a previously unrecognized potential source of IL-17 in sepsis." (PMID 41565647, 2026). "Fourth, the identification of the IL-10, Semaphorin 3e, and IL-17F as the top responders to the polymicrobial sepsis that are being suppressed by the NTCI." (PMID 41229427, 2025). "This underscores the function of IL-17F as the top inflammatory mediator of uncontrolled bacterial infections evolving into sepsis." (PMID 41229427, 2025). "Furthermore, IL-17F level was greatly decreased in septic mice receiving C5a blocking antibody, suggesting that IL-17F production was positively regulated by C5a during sepsis." (PMID 23233853, 2012). "In addition to its immune regulatory functions, C5a has been shown to have a significant impact on the plasma levels of IL-17F in sepsis mice induced by LPS- and CLP, with higher levels of C5a correlating with elevated levels of IL-17F." (PMID 41373839, 2025).
spondyloarthritis (4 papers, 2020 to 2022). "IL-17A and IL-17F together with their coreceptor (IL-17RA/RC) were reported to play a significant role in the pathogenesis of spondyloarthritis." (PMID 34744511, 2021). "As ILC3s are enriched in spondyloarthritis synovial tissue, production of IL-17A and IL-17F by these cells could offer an explanation as to why ustekinumab, which targets the p40 subunit common to both IL-12 and IL-23, was also not efficacious in axial spondyloarthritis." (PMID 33329560, 2020).
abscesses (3 papers, 2015 to 2019). "In psoriatic lesions, IL-17A, IL-17E, and IL-17F are involved in neutrophil accumulation, followed by the formation of epidermal micro abscesses." (PMID 32010143, 2019). "IL-23 injection induced skin inflammation in the ears, as demonstrated by increased histology scores of multiple parameters (inflammation, abscesses, acanthosis, ulceration, parakeratosis), as well as mRNA expression levels of IL-17A, IL-17F, IL-22 and TNFα, compared with saline treated mice." (PMID 27905482, 2016).
acute myeloid leukemia (3 papers, 2014 to 2022). Acute myeloid leukemia (AML) is a group of neoplasms arising from precursor cells committed to the myeloid cell-line differentiation. "In the present study, we wanted to find out whether polymorphic variants of the genes coding for IL-17A, IL-17F and receptor for IL-23 (as hallmarks of Th17 cells) could be associated with susceptibility to acute myeloid leukemia, disease progression and/or response to therapy." (PMID 24793548, 2014).
autoimmune thyroid disease (3 papers, 2015 to 2023). Inflammatory disease of the thyroid gland due to autoimmune responses leading to lymphocytic infiltration of the gland. "The p.V301M variant was previously reported in a mother and her daughter where the mother presented with autoimmune Addison's disease, autoimmune thyroiditis, premature ovarian insufficiency, and autoantibodies targeting 21-hydroxylase, AADC, and IL-17F." (PMID 37235056, 2023).
Behçet’s disease (3 papers, 2013 to 2023). "In a Chinese Han population, polymorphisms of the IL-17F gene were associated with the Vogt-Koyanagi-Harada syndrome (VKHS) and in Korean patients with Behçet’s disease (BD)." (PMID 23977091, 2013).
cutaneous T-cell lymphoma (3 papers, 2016 to 2023). "In cutaneous T-cell lymphoma (CTCL) cell lines mutated SOCS1 boosted IL17F expression via the IL2-JAK3-STAT5 pathway." (PMID 32922661, 2020). "The mRNA expression level of IL-17F has been demonstrated increased in cutaneous T-cell lymphoma (CTCL) skin lesions and was also associated with progression of CTCL." (PMID 26812681, 2016). "Among the poor prognosis-related genes, TRABD2B (also known as TIKI2), IL17F, and GALNTL6 were reported to be related to the oncogenesis of renal cell carcinoma, cutaneous T-cell lymphoma, and thyroid carcinoma, respectively." (PMID 36816541, 2023).
emphysema (3 papers, 2021 to 2025). "Furthermore, Il17a and Il17f dual deficient mice were protected against enlargement of airspaces (emphysema) due to long-term cigarette exposure." (PMID 34075087, 2021). "To assess the potential involvement of IL-17F in the PPE-induced emphysema model, we used an anti-IL-17F neutralizing antibody." (PMID 40461699, 2025). "T-helper cells are characterized by the production of IL-17A, IL-17F, and IL-22, which can be released by eosinophils, neutrophils, CD8+ T cells, basophils, and mast cells, also playing a decisive role in experimental models of emphysema treated with elastase." (PMID 37834157, 2023).
experimental autoimmune encephalomyelitis (3 papers, 2017 to 2024). An autoimmune demyelinating disease of the central nervous system that is produced experimentally in animals by the injection of homogenized brain or spinal cord in Freund's adjuvant. "Knockout ACT1 (a key transcription factor for signals mediated by IL-17A, IL-17F, and IL-17C) reduced the number of infiltrating inflammatory cells and ameliorates experimental autoimmune encephalomyelitis." (PMID 37581321, 2024).
hidradenitis suppurativa (3 papers, 2023 to 2026). A chronic suppurative and cicatricial disease of the apocrine glands occurring chiefly in the axillae in women and in the groin and anal regions in men. "Both, hidradenitis suppurativa and VKHD are driven by IL-17A and IL-17F." (PMID 41142785, 2025).
influenza (3 papers, 2018 to 2022). An acute viral infection of the respiratory tract, occurring in isolated cases, in epidemics, or in pandemics; it is caused by serologically different strains of viruses (influenzaviruses) designated A, B, and C, has a 3-day incubation period, and usually lasts for 3 to 10 days. "Administration of the novel virus-like particle based vaccine elicited influenza-specific CD4+ and CD8+ T-cell responses and the induction of the cytokines IFN-γ, IL-17A, IL17F, IL-5, IL-13, IL-9, IL-10 and IL-21." (PMID 30573748, 2018).
liver disease (3 papers, 2016 to 2025). "A study investigating the mechanistic differences between IL-17A and IL-17F in the context of liver disease, using transcriptional network analysis, revealed distinct pathway activation profiles between the two cytokines." (PMID 41200179, 2025). "IL-17F expression declines progressively with increasing severity of liver disease, independently of IL-17A." (PMID 41200179, 2025). "Another IL-17 family member, IL-17F, does not have a currently defined role in hepatic disorders." (PMID 26895034, 2016).
melanoma (3 papers, 2022 to 2024). A malignant, usually aggressive tumor composed of atypical, neoplastic melanocytes. "A recent evaluation of melanoma patients receiving combination anti-CTLA-4 and anti-PD-1 found that increased IL-17a/IL-17f signaling was positively associated with immune infiltration and improved clinical outcomes; however, this relationship did not extend to patients treated with monotherapy." (PMID 39403935, 2024). "Among melanoma, a lower CTL level indicates better patient survival, but only when IL-17B or IL-17F has a high expression level (p < 0.05)." (PMID 36159856, 2022). "Treg signature genes CXCR5, TNFRSF9, CCR7, STAT1, GBP4, and EOMES were significantly upregulated in the young cohort and were correlated with higher survival in melanoma, while ID3, IL-17A, IL-17F, RDH10 and IL-11 were significantly upregulated in the old cohort." (PMID 36135194, 2022).
meningitis (3 papers, 2018 to 2025). A disorder characterized by acute inflammation of the meninges of the brain and/or spinal cord. "have also found inflammatory markers elevated in the CSF during VZV-related meningitis, including interferon gamma, interleukins IL-6, IL-8, IL-10, IL-17F, IL-1RA, chemokines CXCL-9, CXCL-10, CCL-2 and G-CSF." (PMID 40416981, 2025). "IL-17F was not upregulated significantly in non-TBE meningitis, and its concentration in admission CSF tended to be lower than in TBE (p = 0.066) (right side panels)." (PMID 29678185, 2018).
oral cancer (3 papers, 2022 to 2025). "Then it was discovered that IL-17A rs2275913 acted as risk factors for gastric, cervical, colorectal and oral cancer, and IL-17F rs763780 for cervical and oral cancer." (PMID 36300118, 2022). "Three articles reported a protective role of IL-17F in oral cancer while the fourth one suggested a protumorgenic effect for IL-17F." (PMID 35012470, 2022). "Four articles investigated the expression of IL-17F in oral cancers." (PMID 35012470, 2022). "Previous studies have shown that IL-17F suppresses VM in oral tongue squamous cell carcinoma; HIF-1α/EphA2/Laminin-5γ2 axis downregulation inhibits hypoxia-induced VM in oral cancer; SOX7 inhibits VM by downregulating VE-cadherin in OSCC." (PMID 41502523, 2025). "To conclude, IL-17F protein in tissue and serum, but not in saliva, seems to possess an antitumorigenic role in oral cancers." (PMID 35012470, 2022).
prostate carcinoma (3 papers, 2020 to 2022). A carcinoma that arises from epithelial cells of the prostate gland. "Elevated IL-17F concentration occurs, i.e., in prostate cancer." (PMID 32855976, 2020).
thymoma (3 papers, 2016 to 2025). A neoplasm arising from the epithelial cells of the thymus. "At least in APECED and thymoma, the development of cytokine autoantibodies is not limited to IFNs as they develop autoantibodies to other cytokines including IL-17A, IL-17F, IL-22, IL-12, and IL-1A." (PMID 40304722, 2025). "IL-17F, IL-12p70 or type I IFN, reported in thymoma patients." (PMID 38035080, 2023).
type 1 diabetes (3 papers, 2015 to 2024). "Together these data indicate that IL-17F possesses similar pathogenic activities to IL-17A in mouse β-cell lines and islets and is likely to be a type 17 associated pathogenic factor in type 1 diabetes." (PMID 32753746, 2020). "Type 17 immune responses, typified by the production of the cytokines IL-17A and IL-17F, have been implicated in the development of type 1 diabetes in animal models and human patients, however the underlying pathogenic mechanisms have not been clearly elucidated." (PMID 32753746, 2020). "Thus we speculate that IL-17F deficient or IL-17F/IL-17A doubly deficient NOD mice may exhibit more protection from type 1 diabetes than IL-17A deficient NOD." (PMID 32753746, 2020). "The elevated expression of IL-17E and IL-17F in circulating lymphocytes of type 1 diabetes patients, compared to controls, was also reflected in gene expression levels." (PMID 38714671, 2024). "Firstly that IL-17F and IL-17A could be functionally redundant in type 1 diabetes and that both genes must be inactivated or inhibited for any potential type 1 diabetes protection to eventuate." (PMID 32753746, 2020). "In contrast to IL-17A, the role of IL-17F in type 1 diabetes pathogenesis is largely unstudied." (PMID 32753746, 2020). "Similarly, interventions that block IL-17F and IL-17A simultaneously may have improved therapeutic utility in type 1 diabetes compared to interventions that block either cytokine alone." (PMID 32753746, 2020). "Alternatively IL-17F may have a more important role in type 1 diabetes pathogenesis than IL-17A." (PMID 32753746, 2020).
alopecia areata (2 papers, 2021 to 2024). Loss of scalp and body hair involving microscopically inflammatory patchy areas. "It found that people with alopecia areata had increased plasma levels of the Type 2 cytokines IL-33, IL-31 and IL-17E (IL-25), in addition to the Type 17 cytokines IL-17A, IL-21, IL-23 and IL-17F." (PMID 38892934, 2024).
arteriosclerosis (2 papers, 2023 to 2024). A vascular disorder characterized by thickening and hardening of the walls of the arteries. "In addition, no data or findings have been published on the extent to which inhibition of IL-17A or IL-17F contributes to the suppression of arteriosclerosis." (PMID 39519167, 2024). "Both IL-17A and IL-17F inhibition showed preventive effects against arteriosclerosis." (PMID 39519167, 2024).
arteritis (2 papers, 2019 to 2024). An inflammatory process affecting an artery. "The aim of this study was to examine the association of rs2275913 IL17A and rs2397084, rs11465553 and rs763780 IL17F gene polymorphisms with histopathological changes in transplanted kidney biopsies such as: glomerulitis, tubulitis, arteritis, cell infilitration and fibrosis." (PMID 30961540, 2019). "It still needs further investigation to elucidate whether IL-17F contributes much less than IL-17A in mediating IL-17RA-downstream cascades for leukocyte recruitment and aortic inflammation in our model and KD-related arteritis." (PMID 38451335, 2024).
atopic dermatitis (2 papers, 2018 to 2021). "IL-17F is also increased in sera of atopic dermatitis patients and positively correlates with higher clinical score." (PMID 30127781, 2018).
autoimmune uveitis (2 papers, 2015 to 2025). An autoimmune form of uveitis (disease). "A study of autoimmune uveitis and its animal model (EAU) demonstrated that blocking IL-17A alone in autopathogenic Th17 cells did not reduce their pathogenicity, but increased the expression of GM-CSF and IL-17F." (PMID 40621455, 2025).
Bcc (2 papers, 2022 to 2024). "However, we also performed IL-17F measurements and found reduced concentrations of the cytokine both in plasma and in sputum samples of patients with Bcc infection compared to Bcc-free group." (PMID 39011515, 2024).
celiac disease (2 papers, 2018 to 2024). An autoimmune genetic disorder with an unknown pattern of inheritance that primarily affects the digestive tract. "We found, as in celiac disease, strong upregulation of IL-17 signaling and Th17 cell differentiation in EED including induction of IL21, IL6, IL17A IL17F, IL22, IFNG, IL21R, and IL2RA." (PMID 39300663, 2024).
cerebral malaria (2 papers, 2021 to 2024). A sequestration of Plasmodium falciparum in the brain, which can cause coma and/or seizures. "Variants in IL17F and IL17RA have been found associated with cerebral malaria and similar variation may contribute to the outcome of schistosome infection." (PMID 33659002, 2021).
cervical cancer (2 papers, 2012 to 2022). A primary or metastatic malignant neoplasm involving the cervix. "In the present study, we analyzed two single-nucleotide polymorphisms (SNPs) in the IL17A (rs2275913) and IL17F (rs763780) in 311 cervical cancer patients and 463 controls using TaqMan assays." (PMID 23049595, 2012). "Further studies in different population and with a larger size of samples are needed to identify the association between the IL17A and IL17F genes and the risk of cervical cancer." (PMID 23049595, 2012). "In this study, we aimed to determine the association between the polymorphisms of IL17 (IL17A and IL17F) and the risk of cervical cancer in Chinese women." (PMID 23049595, 2012). "However, it remains unknown whether genetic polymorphisms in IL17A and IL17F influence the risk of cervical cancer development." (PMID 23049595, 2012). "In the present study, the results showed that the SNP rs2275913 of IL17A, but not the SNP rs763780 of IL17F was associated with the susceptibility of cervical cancer." (PMID 23049595, 2012).